CDKN1A (cyclin dependent kinase inhibitor 1A)
Diseases named in the same sentence as CDKN1A in open-access papers (continued):
Sharing a sentence is not in itself a finding about the gene and the disease.
glioma (continued). "Furthermore, CDKN1A was found to be involved in AKT-mediated TMZ resistance of glioma cells." (PMID 33621203, 2021). "Moreover, CDKN1A was found to be involved in AKT-mediated TMZ resistance of glioma cells." (PMID 33621203, 2021). "We then treated TMZ-resistant glioma cells with the specific inhibitor to AKT, MK2206, and found that MK2206 treatment significantly suppressed phosphorylation of CDKN1A at Ser473." (PMID 33621203, 2021). "To verify the promoting effect of CDKN1A on cell chemoresistance, we detect CDKN1A expression in TMZ-resistant glioma cell lines (U87-R and T98G-R cells) and their parental cell lines (U87 and T98G cells)." (PMID 33621203, 2021). "This would be in line with a previous report showing that BMP7 decreases proliferation of a glioma cell line through cell cycle arrest in the G1 phase, through the modulation of CDK2, CDKN1A and pRB expression." (PMID 25860932, 2015). "In this study, we focused on Cell Cycle Protein Dependent Kinase Inhibitor 1A (CDKN1A), which is a regulator of the E2F1 transcription factor and may play a key role in DDR‐related signaling pathways in gliomas and influence TMZ resistance." (PMID 38600891, 2024). "Furthermore, by colony formation assay, transient transfection assay and western blot, we found that CDKN1A was highly expressed in TMZ-resistant glioma cells and involved in AKT-mediated TMZ resistance of glioma cells." (PMID 33621203, 2021). "Furthermore, these findings suggest that MAGED2 can stimulate the growth of U251-MG cells by targeting CDKN1A, suggesting that MAGED2 may serve as a novel target in the clinical treatment of glioma." (PMID 35892426, 2022). "In summary, the results of this study indicate that CUL4B promotes TMZ resistance in GBM cells by epigenetically repressing CDKN1A transcription, CUL4B is a significant clinical prognostic factor and may serve as a promising therapeutic target for the treatment of gliomas." (PMID 33869025, 2021). "In addition, the expression levels of CDKN1A might be negative correlation with TMZ activity in 79 glioma cells from CellMinerCDB." (PMID 33621203, 2021).
pancreatic cancer (44 papers, 1997 to 2026). "In line with this assumption, the CDKN1A promoter hypermethylation was found in various cancers, such as lung, prostate, breast and pancreatic cancer, and leukemia." (PMID 39456618, 2024). "In our work, we also showed that the overexpression of SOX9 in two pancreatic cancer cell lines, BxPC-3 and Colo357, results in increased cell proliferative activity and decreased CDKN1A expression levels." (PMID 35884771, 2022). "To further elucidate the antiviral function of CDKN1A, we knocked down the expression of CDKN1A in two more pancreatic carcinoma cell lines, MIA PaCa‐2 and PANC‐1." (PMID 33037696, 2020). "qRT-PCR analysis using 20 pairs of pancreatic cancer and adjacent normal tissues showed significantly higher CDKN1A and KLF2 expression in the cancer tissues." (PMID 30367681, 2018). "DUXAP8 promoted pancreatic cancer cell growth by epigenetically regulating CDKN1A and KLF2." (PMID 35794983, 2022). "This study provides the first direct evidence that DUXAP8 is a critical and powerful regulator of genes involved in pancreatic cancer progression through silencing CDKN1A and KLF2 in the nucleus, indicating that DUXAP8 is a potential therapeutic target of pancreatic cancer." (PMID 30367681, 2018). "DUXAP8 induced increase in pancreatic cancer cell proliferation and tumorigenesis may be partly mediated via epigenetically silencing CDKN1A and KLF2 transcription by binding with EZH2 and LSD1." (PMID 30367681, 2018). "In pancreatic cancer, down-regulation of METTL16 leads to decreased m6A modification of cyclin-dependent kinase inhibitor 1A (CDKN1A, also known as p21) mRNA, which in turn reduces the expression of the p21 protein." (PMID 41459114, 2026). "Considering these data, the results we acquired also suggest that in pancreatic cancer cells, SOX9 is a negative regulator of CDKN1A activity." (PMID 35884771, 2022). "In all the investigated pancreatic cancer cell lines, the downregulation of SOX9 led to an increase in the levels of the cell cycle inhibitor protein (CDKN1A)." (PMID 35884771, 2022). "In pancreatic carcinoma, DUXAP8 promotes tumor growth through epigenetically silencing CDKN1A and KLF2." (PMID 34957112, 2021). "By epigenetically silencing CDKN1A an KLF2, DUXAP8, upregulated in pancreatic cancer, promoted growth of pancreatic cancer." (PMID 32185172, 2020). "In pancreatic cancer, DUXAP8 enhanced cancer cell proliferation by epigenetically silencing CDKN1A and KLF2." (PMID 32849765, 2020). "In pancreatic cancer cells, SAHA induced increased expression of p21cip1/waf1 levels as well as increased acetylation of histone H3 globally and specifically at the CDKN1A promotor." (PMID 31514410, 2019). "To validate the influence of CDKN1A and KLF2 on cellular proliferation of pancreatic cancer cells, we knocked down CDKN1A and KLF2 expression in BxPC-3 cells." (PMID 30367681, 2018). "This screening also identified CDKN1A (p21) and CDKN1B (p27) as upregulated genes by GPC1-depletion in HPDE cell lines and pancreatic cancer cell lines." (PMID 29245923, 2017). "In addition, USP22 was shown to induce cell cycle protein-dependent kinase inhibitor 1A (CDKN1A) in pancreatic cancer, and MDM2 inhibitors enhanced the anti-pancreatic cancer effect of USP22 overexpression." (PMID 35884607, 2022). "Over-expression of Cyclin D1 was found to confer gemcitabine and cisplatin resistance to pancreatic cancer cell; CCNE1, CDK2, and CDKN1A, previously reported to be up-regulated by gemcitabine as confirmed in our study, were also implied in chemotherapy resistance." (PMID 33925948, 2021).
pancreatic cancer (continued). "Next, to further investigate whether CDKN1A and KLF2 are involved in the enhanced cellular proliferation induced by DUXAP8 in pancreatic cancer cells, we performed rescue experiments." (PMID 30367681, 2018). "Furthermore, by inducing deubiquitination and inhibiting the degradation of PTEN, USP22 could induce cyclin‐dependent kinase inhibitor 1A (CDKN1A, also symboled as p21) expression in pancreatic cancer." (PMID 34743406, 2022). "Additionally, CDKN1A was induced by SOX2 siRNAs in the presence of cycloheximide, suggesting the direct suppression of CDKN1A by SOX2, as has been reported in pancreatic cancer cells." (PMID 26846300, 2016).
glioblastoma (39 papers, 2009 to 2025). The most malignant astrocytic tumor (WHO grade IV). "In this retrospective study, our objective was to identify polymorphic variants of CDKN1A, specifically c.93C > A (codon 31 Ser31Arg), and investigate its potential impact within the scope of bevacizumab therapy for glioblastoma multiforme." (PMID 37730565, 2023). "Although our sample size is relatively small, these findings indicate a potential association between the Arg/Arg and Ser/Arg genotypes of the CDKN1A c.93C > A polymorphism and the beneficial effect of bevacizumab in glioblastoma treatment." (PMID 37730565, 2023). "To address this gap, we conducted a retrospective study focusing on the potential role of CDKN1A functional polymorphism as a predictive marker in patients with glioblastoma multiforme within the Taiwanese population." (PMID 37730565, 2023). "Presumably, the Gol1 aptamer promotes the overexpression of several components of the PI3K-Akt pathway that are positively associated with apoptosis and differentiation and negatively associated with proliferation and cell growth in human glioblastoma cells, such as the CDKN1A and PKN2 genes." (PMID 39940838, 2025). "LncEPAT was reported to be a functional oncogene in glioblastoma, and lncEPAT silencing increased the expression of cell aging-associated genes, such as CDKN1A, CLUSTERIN, and DKK1, indicating that lncEPAT exerts a repressive function in glioblastoma cell senescence." (PMID 38228673, 2024). "On opposite, CDKN1A shows genomic alterations in only less than 1% of glioblastoma." (PMID 41350483, 2025). "Moreover, CDKN1A mRNA was shown to be upregulated in glioblastoma cells and tissues and contributed to temozolomide resistance acting downstream of Akt." (PMID 39594738, 2024). "In glioblastoma, CUDC-907 induces G1 cell cycle arrest through CDKN1A promoter hyperacetylation-driven transcriptional activation and downregulation of CDK1, while in lung fibroblast cells, CUDC-907 blocks G1 and S phase." (PMID 35205815, 2022). "Based on what is known regarding the regulation of E2F transcription factors, we decided to test if the previously identified Msi1 direct targets CDK6, CDKN1A/p21, CDKN1B/p27 affect E2F2 and E2F8 levels in glioblastoma cells." (PMID 33804958, 2021).
bladder cancer (35 papers, 2013 to 2026). "Among tumor suppressors altered in bladder cancer, CDKN1A, which encodes the cyclin-dependent kinase inhibitor p21, is recurrently inactivated and downregulated, supporting its potential as a target for tumor suppressor replacement." (PMID 42144924, 2026). "Among these, bladder carcinoma stands out with the highest mutation burden within CDKN1A/p21, affecting 11.99% of patients." (PMID 38139316, 2023). "Mutations in CDKN1A, a known bladder cancer driver gene, were the most significant event occurring in 17% of tumors." (PMID 35311085, 2022). "In The Cancer Genome Atlas (TCGA) dataset, 14% of invasive bladder cancers have mutations in CDKN1A encoding the cyclin-dependent kinase inhibitor p21CIP1." (PMID 28049532, 2017). "Importantly, mutations in RBM10 and CDKN1A are also significantly more abundant in bladder cancers of men than of women." (PMID 41062697, 2025). "In contrast, American patients with bladder cancer tend to harbor mutations that disrupt signaling by GPCR, with CDKN1A, IRS4 and KMT2D identified in the 6-gene set." (PMID 40768543, 2025). "Genistein stops bladder cancer cells from multiplying by increasing CDKN1A (p21/WAF1) and decreasing cyclin A and cyclin B1." (PMID 40078339, 2025). "For example, circZKSCAN1 up-regulated cyclin-dependent kinase inhibitor 1A expression by sponging miR-1178-3p, which suppressed the aggressive biological behaviors in bladder cancer." (PMID 36691031, 2023). "The overexpression of CDKN1A can promote apoptosis, cell cycle arrest and bladder cancer metastatic ability." (PMID 36430344, 2022). "miR‐96‐5p upregulation acts as an antiapoptotic factor in bladder cells, as it negatively regulates specific targets such as CDKN1A, which is involved in cell cycle regulation and DNA damage pathway in bladder cancer." (PMID 31254352, 2019). "In a previous study of patients with advanced bladder carcinoma undergoing radical surgery showed that patients with tumors that maintained CDKN1A (p21) expression had increased survival relative to patients with loss of CDKN1A expression." (PMID 23809295, 2013). "Moreover, GABPA regulates the expression of CDKN1A and serves as a tumor suppressor in bladder cancer." (PMID 34338139, 2021). "Many protein coding genes from the newly identified ceRNA network were reported as oncogenes and/or tumor suppressors participating in bladder cancer development and progression, such as CDKN1A, HMGA2 and MYC, which also was considered as promising therapeutic targets for bladder cancer." (PMID 27863388, 2016). "In addition to identifying CDKN1A mutations, we have highlighted inactivating FAT1 mutations as possible bladder cancer drivers, on the basis of protein-truncating mutations and deletions in our own and TCGA data." (PMID 24777035, 2014). "We validated the STAG2 and CDKN1A changes detected by whole-genome sequencing using Sanger sequencing in the discovery set of tumours, and then undertook replication testing in a set of 35 additional bladder cancers." (PMID 24777035, 2014). "Genistein inhibits bladder cancer cells proliferation by arresting the cell cycle at the G2/M phase via suppression of cyclin A and cyclin B1, and upregulation of CDKN1A (p21/WAF1)." (PMID 33996570, 2021). "For instance, the most similar pair in bladder carcinoma set is formed by the networks of FBXW7 and CDKN1A." (PMID 31253832, 2019). "The pathway view of genes frequently altered in bladder carcinoma generated by TCGA1 coheres with this observation, as both CDKN1A and FBXW7 are listed as negative regulators of CCNE1 and cell cycle progression." (PMID 31253832, 2019). "For instance, the similarity observed between CDKN1A and FBXW7 networks underscores the possibility that cell cycle dysregulation in bladder carcinoma can be achieved by directly inactivating a CDK inhibitor or alternatively, by inactivating a regulatory protein." (PMID 31253832, 2019).
cervical carcinoma (34 papers, 1998 to 2025). A carcinoma arising from either the exocervical squamous epithelium or the endocervical glandular epithelium. "Similarly variant rs1801270 in CDKN1A gene are associated with development of cervical cancer in Han Chinese, Brazilian, and Iranian populations." (PMID 37667176, 2023). "Acute lncRNA Dino overexpression caused an increase in Cdkn1a expression in cervical cancer cells." (PMID 34364390, 2021). "EBIC depletion in the HPV18 positive HeLa cervical carcinoma line inhibited proliferation by affecting the expression of cell cycle genes such as p21CIP1 (CDKN1A), cyclin E, and CDK2." (PMID 32326624, 2020). "In the 1990s, ETV4 was regarded as a tumor suppressor gene because it was able to increase luciferase expression driven by the CDKN1A promoter in SiHA cervical cancer cells whereas its deletion reduced CDKN1A levels in Saos2 osteosarcoma cells." (PMID 32791988, 2020). "In addition, CDK inhibitors are transcriptional targets of EMT-TFs; SNAIL activated p21CIP1-encoding gene CDKN1A; and SLUG induced both CDKN1A and CDKN1B (codes for p27KIP1) in cervical carcinoma cells." (PMID 37259089, 2023). "miR-125a, which modulates CDKN1A, was downregulated in patients with cervical cancer who did not respond to standard treatment." (PMID 38963803, 2024). "In terms of mechanism research, increased CDKN1A expression and Bax/Bcl-2/caspase-3 signaling pathway might be involved in the G2/M phase arrest and increased apoptosis in RIF1-silenced cervical cancer cells." (PMID 29291010, 2017).